MTCO1P40 (MT-CO1 pseudogene 40)
Gene: Processed pseudogene on chromosome 17 (53,105,734 to 53,106,358, forward strand). Ensembl gene ENSG00000262902.
Diseases named in the same sentence as MTCO1P40 in open-access papers:
MTCO1P40 is named in the same sentence as 2 diseases in open-access papers, as found by Europe PMC text mining. Sharing a sentence is not in itself a finding about the gene and the disease. The quoted sentences say what the papers report.
schizophrenia (1 paper, 2024). A major psychotic disorder characterized by abnormalities in the perception or expression of reality. "From total 66 DEGs, we identified 11 (16%) as pseudogenes, which comprised two main groups: mitochondrial pseudogenes increased in females (MTND1P23, MTCO1P12, MTCO1P40, and MTND2P28) and ribosomal pseudogenes increased in male schizophrenia patients (RPS4XP22, RPS16P4, and RPS28P7)." (PMID 39068467, 2024).
MTCO1P40 also shares sentences with these, for which no sentence is quoted: Obesity (1 paper).